CTBP1 (C-terminal binding protein 1)
Diseases named in the same sentence as CTBP1 in open-access papers (continued):
Sharing a sentence is not in itself a finding about the gene and the disease.
ovarian carcinoma (8 papers, 2016 to 2024). A malignant neoplasm originating from the surface ovarian epithelium. "Together, these data strongly suggest that CTCF mediates ovarian cancer metastasis by regulating the expression of metastasis-associated genes, including CTBP1, SERPINE1 and SRC." (PMID 28977939, 2017). "Hence, both immunofluorescence and co-immunoprecipitation assays suggest that Pinin physically associates with both CtBP1 and CtBP2 proteins in the nuclei of ovarian cancer cells." (PMID 26871283, 2016). "CtBP1/2 were found to be overexpressed in multiple subtypes of ovarian cancer cells by western blot analysis." (PMID 34253710, 2021). "Two DNA-PK selective inhibitors, KU-0060648 and NU7441, were employed as probe to investigate the regulatory role of DNA-PK during DDR in the CtBP1/2 KD ovarian cancer cells." (PMID 34253710, 2021). "CtBP1/2 was found to be abnormally overexpressed in several ovarian cancer cell lines, including MCAS, SKOV3, RMG1, and RMUGL, and a very weak signal was found in human normal ovarian epithelium (HOSE)." (PMID 34253710, 2021). "Recent studies have shown that C-terminal binding protein-1 and -2 (CtBP1/2) are overexpressed in ovarian cancer, and CtBP2 expression is correlated with poor prognosis." (PMID 32332713, 2020). "Based on the prior demonstration of CtBP1/2 overexpression in ovarian cancer, and poor prognosis related to CtBP2 expression, we investigated the cellular CtBP dependency of HGSOC." (PMID 32332713, 2020). "Knockdown of Pinin in ovarian cancer cells resulted in specific reduction of CtBP1 protein expression, cell adhesion, anchorage-independent growth, and increased drug sensitivity." (PMID 26871283, 2016). "Our characterization also indicates that Pinin interacts with both human CtBP1 and CtBP2 proteins in the nuclei of ovarian cancer cells." (PMID 26871283, 2016). "It is thought that CtBP1/2 overexpression contributes to the abnormality of ovarian cancer cells." (PMID 34253710, 2021). "The prior findings of CtBP1/2 overexpression in ovarian cancer prompted us to investigate whether HGSOC cells exhibit dependency on CtBP." (PMID 32332713, 2020). "Whole transcriptomic comparison of next-generation RNA sequencing data between control ovarian cancer cell lines and cancer cell lines with respective knockdown of Pinin, CtBP1, and CtBP2 expression also showed reduced expression of CtBP1 mRNA in the Pinin knockdown cell lines." (PMID 26871283, 2016). "In support of our conclusion that CtBP represses the drug resistance of ovarian cancer cells, the pair-wise comparison between cisplatin-resistant and cisplatin-sensitive A2780 cancer cells disclosed that cisplatin-resistant cells significantly downregulated both CtBP1 and CtBP2." (PMID 37151877, 2023). "To further evaluate the CTCF-mediated regulation of the expression of metastasis-associated genes, we analyzed the correlations between CTCF and SRC, CTBP1 and SERPINE1 gene expression in 255 human ovarian cancer specimens obtained from the GSE13876 database." (PMID 28977939, 2017). "Western blot analysis revealed that CTCF protein expression was directly correlated with that of CTBP1 (R=0.69, P<0.01), SERPINE1 (R=0.56, P<0.05) and SRC (R=0.83, P<0.0001) in 18 fresh ovarian cancer specimens." (PMID 28977939, 2017). "We compared the expression of Pinin, CtBP1, and CtBP2 in these three knockdown cell lines with the control SKOV3-IPLuc cancer cell line, and a pair of SKOV3-IPLuc ovarian cancer cell lines with knockdown of CtBP1 and CtBP2 expression, respectively." (PMID 26871283, 2016).
ovarian carcinoma (continued). "In addition, we performed IHC analysis to examine the expression of CTCF and SRC, CTBP1 and SERPINE1 in a different cohort comprising 40 ovarian cancer specimens." (PMID 28977939, 2017). "Indeed, we observed a direct correlation between CTCF and CTBP1, SERPINE1, and SRC expression in cell lines, xenografted tumors and human ovarian cancer specimens." (PMID 28977939, 2017). "Fluorescence microscopy of ovarian cancer cells stained with fluorescently labeled Pinin and CtBP2 antibodies showed that they were co-localized in the nuclei of the cells, similar to the co-localization of CtBP1 with Pinin (data not shown)." (PMID 26871283, 2016).
breast tumor (7 papers, 2015 to 2022). "To analyze CTBP1 role in breast tumor progression, we first analyzed CTBP1 modulation effect on MDA-MB-231, 4T1 and Hs578T BrCa cell adhesion and migration, both cell lines representing advanced stages of TNBC." (PMID 29568399, 2018). "CTBP1, a co-repressor of tumor suppressor genes, increases breast tumor growth in vitro and in preclinical orthotopic xenograft models." (PMID 28460433, 2017). "CtBP1 increased breast tumor growth in MeS mice modulating multiple genes and miRNA expression implicated in cell proliferation, progenitor cells phenotype, epithelial to mesenchymal transition, mammary development and cell communication in the xenografts." (PMID 26933806, 2016). "All of these findings suggest that CTBP1 inhibition mimics miR-644a overexpression in inhibition of breast tumor growth and metastasis." (PMID 27409664, 2016). "Altogether these results suggest that Cyclin D1 is an important CtBP1 target modulated in the mammary gland and in breast tumor by MeS." (PMID 26933806, 2016). "Previously, we generated a MeS-like experimental model and found that CTBP1 and MeS increased breast tumor growth by regulating multiple genes and miRNAs involved in cell proliferation, progenitor cells phenotype, EMT, mammary development and cell communication." (PMID 29568399, 2018). "CTBP1 and MeS increased breast tumor growth regulating several genes and miRNAs involved in cell proliferation, self-renewal, mammary differentiation, cell communication, metabolic processes and epithelial-to-mesenchymal transition (EMT) in orthotopic xenografts." (PMID 29568399, 2018).
colon carcinoma (6 papers, 2005 to 2025). "The overexpression of the CTBP1/2 has been reported in various cancer types, such as prostate, leukemia, ovarian, breast and colon cancer." (PMID 40362431, 2025).
developmental delay (6 papers, 2019 to 2025). "We report a further case of a pathogenic, heterozygous, de novo variant in CTBP1 identified by whole exome sequencing in a female with the typical phenotype of global developmental delay, hypotonia, cerebellar dysfunction and failure to thrive." (PMID 36341169, 2022). "Sequencing identified a significant de novo heterozygous missense variant in the gene encoding c-terminal binding protein 1 (CTBP1): CTBP1 (NM_001012614.2): c.991C > T p.(Arg331Trp) as a rare cause of hypotonia, developmental delay and tooth enamel defect syndrome (HADDTS)." (PMID 40959803, 2025). "It has been suggested that C-terminal binding protein 1 (CTBP1), complexin 1 (CPLX1), and phosphatidylinositol glycan anchor biosynthesis class G (PIGG) are possible candidates for developmental delay, intellectual disabilities, and seizures in WHS patients." (PMID 31297068, 2019).
hepatocellular carcinoma (6 papers, 2009 to 2024). A malignant tumor that arises from hepatocytes. "For example, CTBP1 is listed by Cancer Resource, and TASP1 is also a drug target, which is used to combat novel diseases whose candidate genes are targeted by HNF4alpha splice variants in hepatocellular carcinomas, as well as PNKP and RAG2." (PMID 28691014, 2017). "CTBP1 upregulation and the resulting E-cadherin downregulation were correlated with the progression of human hepatocellular carcinoma (HCC)." (PMID 34199293, 2021). "However, expression of the variant seems to be important in tumors as CtBP1splice was also detected in breast, colon and hepatocellular carcinoma cells which lack full length CtBP1 expression (data not shown)." (PMID 19216735, 2009).
metabolic syndrome (5 papers, 2016 to 2020). A cluster of metabolic risk factors for CARDIOVASCULAR DISEASES and TYPE 2 DIABETES MELLITUS. "Moreover, in this study, the authors analyzed the effect of metabolic syndrome and CTBP1 on miRNA regulation, showing that CTBP1 modulated several microRNAs implicated in cell proliferation and tumor progression." (PMID 33202793, 2020). "Metabolic syndrome and CTBP1 were able to modulate miR-381-5p levels in xenografts generated in mice, and, in particular, CTBP1 promoted cell adhesion and migration by miR-181-5 repression." (PMID 33202793, 2020).
epilepsy (4 papers, 2020 to 2025). A brain disorder characterized by episodes of abnormally increased neuronal discharge resulting in transient episodes of sensory or motor neurological dysfunction, or psychic dysfunction. "The hemizygosity of CTBP1 gene was described to be related to the progression of epilepsy in WHS patients." (PMID 33217222, 2021). "In certain patients with the smallest micro-deletions in 4p16.3, a cluster of four genes including NSD2 and CTBP1 is deleted, implicating CTBP1 in neurodevelopmental disorders including epilepsy in some WHS patients." (PMID 33192249, 2020). "As advanced elsewhere C-Terminal-binding protein 1, a transcriptional co-repressor gene (CTBP1) [OMIM#602618], could be a good candidate for seizures/epilepsy in WHS." (PMID 33627176, 2021).
prostate tumor (4 papers, 2016 to 2024). "Although, that report demonstrated that CtBP1 is crucial for prostate tumor growth; it was unsuccessful to determine CtBP1 role in prostate carcinogenesis." (PMID 26933806, 2016). "We previously found that CtBP1 depletion impairs prostate tumor growth in mice with MeS." (PMID 26933806, 2016). "Here, we integrated in vitro (prostate tumor cell lines) and in vivo (MeS/PCa NSG mice) models with molecular and cell biology techniques to investigate MeS/CTBP1 impact over PCa progression, particularly over cell adhesion, mRNA/miRNA expression and PCa spontaneous metastasis development." (PMID 30931931, 2019).
esophageal squamous cell carcinoma (3 papers, 2021 to 2023). Esophageal squamous cell carcinoma (ESCC) is a type of esophageal carcinoma (EC) that can affect any part of the esophagus, but is usually located in the upper or middle third. "circIMMP2L mediates the malignancy of esophageal squamous cell carcinoma (ESCC) by promoting the nuclear retention of CtBP1." (PMID 35884948, 2022).
glioblastoma (3 papers, 2017 to 2023). The most malignant astrocytic tumor (WHO grade IV). "In a glioblastoma cell line with exogenously expressed CTBP1 p.R342W, the interactions of various CtBP-cofactors were reduced with the mutant protein." (PMID 33192249, 2020). "Regarding the first signature network component, hsa-mir-137, hsa-mir-330, hsa-mir-149, hsa-mir-107, hsa-mir-181b were among the miRNAs whose experimentally validated targets (such as CTBP1, CDC42, CDK6, E2F1, VEGFA, AKT1, KAT2B) affect the pathways which play a crucial role in glioblastoma biology." (PMID 28045122, 2017).
autism (2 papers, 2023 to 2025). Persistent deficits in social interaction and communication and interaction as well as a markedly restricted repertoire of activity and interest as well as repetitive patterns of behavior. "Through the PLDLS domain, CTBP1 plays a critical role as a scaffolding protein for transcription factors and chromatin-modifying enzymes usually liked to neurodevelopmental disorders, autism and congenital heart disease." (PMID 40959803, 2025).
Hypertension (2 papers, 2019 to 2024). The presence of chronic increased pressure in the systemic arterial system. "We validated a concordant direction of effect sizes of CTBP1, PPM1G, SEPT2, and KRTCAP3 for gout; SKIV2L for heart failure; and AAK1, MAPKAPK5-AS1, POLA2, RSG1, and WWP2 for hypertension." (PMID 38658550, 2024).
Insulin resistance (2 papers, 2011 to 2024). Increased resistance towards insulin, that is, diminished effectiveness of insulin in reducing blood glucose levels. "CTBP1 (C-terminal binding protein 1) and MAEA (macrophage erythroblast attacher) have effects on adipose tissue functions, which may lead to insulin resistance." (PMID 21754918, 2011).
liver cancer (2 papers, 2023 to 2025). An epithelial or non-epithelial malignant neoplasm that arises from the liver. "CTBP1, a transcriptional co-repressor, is involved in EMT and tumor plasticity and has been linked to sarcomatoid transformation in liver cancer." (PMID 40963856, 2025).
metastatic disease (2 papers, 2019). "Hence, we report for the first time that CTBP1 together with MeS play a crucial role inducing PCa progression from localized to metastatic disease." (PMID 30931931, 2019). "In addition, we show that CTBP1 regulates a cluster of miRNAs that target cell adhesion genes, which could in turn impact over cell adhesion itself and ultimately on the onset of metastatic disease." (PMID 30931931, 2019).
pancreatic cancer (2 papers, 2022 to 2023). "In this study, We found that SH3BP5-AS1 could regulate CTBP1 in pancreatic cancer." (PMID 36397058, 2022).
serous ovarian cancer (2 papers, 2021 to 2022). "In summary, this study discovered that CtBP1/2 played differentially protector of genetic stability and DNA repair pathways in serous ovarian cancer cells." (PMID 34253710, 2021). "Together, these results revealed that CtBP1/2 play a different regulatory role in genomic stability and DSBs repair pathway bias in serous ovarian cancer cells." (PMID 34253710, 2021). "Several enriched key functional pathways, including DDR and apoptosis, had been thoroughly investigated in CtBP1/2 knockdown serous ovarian cancer cells utilizing transcription profile enrichment analysis." (PMID 34253710, 2021). "In light of these findings, it is proposed that DNA-PK be activated for the initial DNA repair and significantly increase the sensitivity to the specific inhibitor of DNA-PK in the CtBP1/2 knockdown serous ovarian cancer cells." (PMID 34253710, 2021). "Overexpression of CtBP1/2 was thought to play regulatory roles in the cell cycle and adhesion of serous ovarian cancer cells." (PMID 34253710, 2021). "It is proposed that CtBP1 or CtBP2 knockdown induce apoptosis in serous ovarian cancer cells, and that CtBP1/2-DKD accelerate the process of apoptosis while failing to generate stable double knockdown cells." (PMID 34253710, 2021). "In this study, we combined whole-transcriptome analysis with multiple DNA damage repair research methods to investigate the role of CtBP1/2 in genomic stability in serous ovarian cancer cells." (PMID 34253710, 2021). "CtBP1/2 contributed to maintain the stability of DNA replication fork and DNA repair in serous ovarian cancer cells." (PMID 34253710, 2021). "Furthermore, CtBP1/2 knockdown significantly disrupted the stability of the DNA replication fork and increased the instability of DNA replication recovery in serous ovarian cancer cells." (PMID 34253710, 2021). "It was implied that CtBP1/2 protect against the degradation of stalled replication forks with opposite directions for the leading and lagging strands and CtBP2 appears to play a dominant protective role in serous ovarian cancer cells." (PMID 34253710, 2021). "However, it is unclear what role CtBP1/2 in DNA replication and DNA damage repair in serous ovarian cancer cells." (PMID 34253710, 2021). "We investigated the correlation of CtBP1/2 genetic alterations with patient overall survival time in serous ovarian cancer patients using TCGA cases to validate the results that disruption of CtBP proteins function would lead to cancer cell apoptosis and increase DNA instability." (PMID 34253710, 2021). "To validate the hypothesis that disrupting CtBP2’s function may inhibit the abnormal growth of cancer cells, we utilized the TCGA via cBioportal to explore the potential correlation of CtBP1/2 genetic alterations with patient’s overall survival time in serous ovarian cancer patients." (PMID 34253710, 2021). "Simultaneously, the lengths of CldU tract formed after breakage were measured, with or without HU exposure, to evaluate the impact of CtBP1/2 knockdown on the DNA replication recover ability in serous ovarian cancer cells." (PMID 34253710, 2021).
T cell lymphoma (2 papers, 2010 to 2017). "However, Ctbp1 exhibited a stable expression profile in the current T-cell lymphoma model." (PMID 28807016, 2017). "To identify suitable reference genes during T-cell lymphoma development, we investigated the expression stabilities of eight commonly used candidate reference genes (Gapdh, Rn18s, Actb, Hprt, B2M, Rplp0, Gusb, and Ctbp1) by RT-qPCR at different time points following the administration of MNU." (PMID 28807016, 2017). "In conclusion, we identified Ctbp1 and Rplp0 as the best reference genes for thymus and spleen, respectively, in an MNU-induced T-cell lymphoma mouse model." (PMID 28807016, 2017).
viral infection (2 papers, 2024 to 2025). "The median expression of some genes (CTBP1, LAPTM4B, CFAP45, DSC2, LAMP1, EXOG, RPS21, and SIRPB1) was higher in bacterial compared to viral infection." (PMID 41496780, 2025).
acute myeloid leukemia (1 paper, 2022). Acute myeloid leukemia (AML) is a group of neoplasms arising from precursor cells committed to the myeloid cell-line differentiation. "Moreover, the fusion involving MAEA::CTBP1 (detected in one SR B-ALL case from our cohort), although with different breakpoints, has already been described in colon adenocarcinoma and acute myeloid leukemia." (PMID 35884588, 2022).
Alzheimer disease (1 paper, 2023). A progressive, neurodegenerative disease characterized by loss of function and death of nerve cells in several areas of the brain leading to loss of cognitive function such as memory and language. "Recently, it was also shown that overexpression of CtBP1 in Alzheimer’s disease rat models induced neuroprotection of hippocampal and cortical neurons and enhanced neuronal activity." (PMID 37060501, 2023). "Moreover, the overexpression of CtBP1 in hippocampal and cortical neurons triggers neuroprotection in rat models of Alzheimer’s disease." (PMID 37060501, 2023).
atherosclerosis (1 paper, 2025). A disease characterized by the build-up of fatty material and calcium deposition in the arterial wall resulting in partial or complete occlusion of the arterial lumen. "This study reveals a novel role for lactate in instigating vascular inflammation during atherosclerosis by coordinating the MCT1/NADH/CtBP1‐dependent transrepressive activity of FOXP1 in ECs." (PMID 39949978, 2025). "In light of studies showing that FOXP1 can transcriptionally repress the NLRP3 inflammasome and inhibit the development of atherosclerosis, we hypothesized that CtBP1 might interact with FOXP1 to modulate VCAM‐1 and ICAM‐1 gene transcription." (PMID 39949978, 2025).
cholangiocarcinoma (1 paper, 2024). A carcinoma that arises from the intrahepatic biliary tree (intrahepatic cholangiocarcinoma) or from the junction, or adjacent to the junction, of the right and left hepatic ducts (hilar cholangiocarcinoma). "In cholangiocarcinoma, CTBP1 protein expression was significantly up-regulated and negatively correlated with E-cadherin protein expression." (PMID 37138491, 2024). "CTBP1 may be involved in regulating and inhibiting the expression of E-cadherin protein in cholangiocarcinoma, thereby promoting tumor EMt." (PMID 37138491, 2024).
chronic myeloid leukemia (1 paper, 2023). "KEGG analysis in the BaF3-T315 cells showed that the chronic myeloid leukemia signaling pathway (genes such as Cdk4, Tgfbr1, Gadd45b, Mdm2, Gadd45g, Polk, Rb1, Ctbp1, and Cdkn2a were enriched) was involved in the I13 treatment." (PMID 37124196, 2023).